CPNE1 (copine 1)
Diseases named in the same sentence as CPNE1 in open-access papers (continued):
Sharing a sentence is not in itself a finding about the gene and the disease.
sarcopenia (2 papers, 2023). Progressive decline in muscle mass due to aging which results in decreased functional capacity of muscles. "The involvement of CPNE1 in sarcopenia is supported by the findings of a genome-wide association study of appendicular lean mass in mice and humans." (PMID 36525128, 2023). "However, sarcopenia is also associated with these diseases and there may be a correlation between CPNE1 expression, disease progression, and muscle atrophy." (PMID 36525128, 2023). "Overall, these results confirm that mice with age-related sarcopenia have lower muscle mass with upregulated CPNE1 and atrophy markers, and a variation in lipid composition." (PMID 36525128, 2023). "To determine whether CPNE1 influenced other genes differentially expressed during age-related sarcopenia, we measured the protein levels of muscle atrophy markers (a’)." (PMID 36525128, 2023). "To determine whether CPNE1 is a key regulator in muscle atrophy, we assessed the characteristics of sarcopenia in young skeletal muscle-derived satellite cells when CPNE1 is overexpressed." (PMID 36525128, 2023). "To conclude, we have identified CPNE1 as a myogenesis modifier in sarcopenia." (PMID 36525128, 2023). "Here, we identify the role of the myogenesis modifier CPNE1 in sarcopenia." (PMID 36525128, 2023). "After establishing a connection between ER stress and characteristics of sarcopenia, we determined whether the impact of CPNE1 overexpression on mitochondrial function in young satellite cells was influenced by the PERK/eIF2α/ATF4 pathway, which is associated with ER stress and the UPR." (PMID 36525128, 2023). "CPNE1 could be a valuable target in alleviating the symptoms of sarcopenia." (PMID 36525128, 2023). "However, the effect and mechanism of CPNE1 on sarcopenia are still unclear." (PMID 36525128, 2023). "These two genes, CPNE1 and STC2, encode proteins that have not yet been formally associated with COPD sarcopenia (i.e., Copine 1, a soluble calcium-dependent membrane-binding protein, and Stanniocalcin 2, a homodimeric glycoprotein hormone involved in the regulation of IGF1)." (PMID 37047427, 2023).
type 2 diabetes (2 papers, 2021 to 2025). "The risk of type 2 diabetes was associated with decreased levels of CPNE1 in the pancreas (Z = −2.1, Q = 0.02), skeletal muscle (Z = −2.1, Q = 0.02), and blood (Z = −2.3, Q = 0.01)." (PMID 34575035, 2021). "Transcription factors co-regulating the pancreatic expression of EDEM2, MYH7B, MAP1LC3A, and CPNE1 genes that associated with type 2 diabetes have been predicted by the hTFtarget tool." (PMID 34575035, 2021). "In addition, further TWAS analysis has revealed that the increased pancreatic expression of EDEM2, MYH7B, MAP1LC3A and decreased levels of CPNE1 are associated with the genetic risk of type 2 diabetes." (PMID 34575035, 2021). "Thus, the TWAS analysis allowed revealing the genetic association between the changes in pancreatic expression of genes such as EDEM2, MYH7B, MAP1LC3A, and CPNE1 and the risk of type 2 diabetes." (PMID 34575035, 2021). "The TWAS analysis has shown that the pancreatic expression of EDEM2, MYH7B, MAP1LC3A, and CPNE1 correlated to a carriage of T2D-associated alleles of GSS and GGT7 is associated with the genetic risk of type 2 diabetes." (PMID 34575035, 2021).
colon cancer (1 paper, 2023). "Similarly, CPNE1 belongs to the copines family that is highly conserved and soluble in eukaryotes, and can augment aerobic glycolysis and facilitate the advancement of colon cancer by modulating the AKT-GLUT1/HK2 pathway." (PMID 37532687, 2023).
depression (1 paper, 2022). "Copine-1 (r = 0.007, P = 1.13 × 10− 2) and complement C4b (r = − 0.007, P = 1.31 × 10− 2) were associated only with depression in brain." (PMID 35870967, 2022).
head and neck squamous cell carcinoma (1 paper, 2023). A squamous cell carcinoma that arises from any of the following anatomic sites: lip and oral cavity, nasal cavity, paranasal sinuses, pharynx, larynx, and salivary glands. "In HNSC (head and neck squamous cell carcinoma), KIRC (kidney renal clear cell carcinoma) and MESO (Mesothelioma), patients with high CPNE1 expression possessed shorter overall survival times." (PMID 37077419, 2023).
hepatocellular carcinoma (1 paper, 2022). A malignant tumor that arises from hepatocytes. "HCCDB, CCLE, HPA and LinkedOmics online databases were used to explore the expression of CPNE1 gene and analyze the co-expression network of CPNE1 in hepatocellular carcinoma." (PMID 35139863, 2022). "To validate whether CPNE1 was overexpressed in LIHC cell lines, we tested the mRNA expression level of CPNE1 in L02 (a human normal liver cell line) and 5 human hepatoma cell lines (MHCC-97H, HepG2, Hep3B, Huh7 and HLF) by using RT-qPCR." (PMID 35139863, 2022). "Our study aimed to investigate the expression and prognostic value of CPNE1 gene in hepatocellular carcinoma (HCC), to explore its functional network in HCC and its effects on biological behaviors." (PMID 35139863, 2022). "Compared with L02 cell, the expression level of CPNE1 in HepG2, MHCC-97H and huh7 was much higher, which indicated the expression level of CPNE1 in human hepatoma cell lines was higher than that in human normal liver cell line." (PMID 35139863, 2022).
large cell carcinoma (1 paper, 2020). A malignant epithelial neoplasm composed of large, atypical cells. "CPNE1 expression differs in large cell carcinoma (LCC), ADC, and SCC subtypes in the GSE19188 dataset, and we observed differential expression between ADC and SCC tumors." (PMID 32201531, 2020).
pancreatic cancer (1 paper, 2024). "Silencing CPNE1 with siRNA reduced both CPNE1 and TRAF2 levels, decreasing pancreatic cancer cell proliferation." (PMID 39061149, 2024).
Parkinson disease (1 paper, 2020). A progressive degenerative disorder of the central nervous system characterized by loss of dopamine producing neurons in the substantia nigra and the presence of Lewy bodies in the substantia nigra and locus coeruleus. "The loci within these eQTL scores have been reported to regulate expression of genes involved in various brain-related processes and disorders, such as neurite outgrowth and Parkinson’s disease (DCAKD, SLC35A4, SEC14L4, SRA1, NMT1, CPNE1, PLEKHM1, UBE3C)." (PMID 32066731, 2020).
rectal cancer (1 paper, 2024). A primary or metastatic malignant neoplasm that affects the rectum. "Computational analysis from both differential expression and survival plots highlighted CTSB and CPNE1, and therefore, these were implicated in colon and rectal cancers." (PMID 38544823, 2024).
rectum adenocarcinoma (1 paper, 2024). An adenocarcinoma arising from the rectum. "However, upon further differential gene expression comparative analysis, it was noted that although all genes except OPRM1 and ADRA1A showed expression in colon and rectal adenocarcinoma, their levels of expression were not as high as CTSB and CPNE1, which demonstrated the maximum expression." (PMID 38544823, 2024).
skin cancer (1 paper, 2025). "Six genes (RBM6, DNAJC18, SPIRE2, CPNE1, SEPT2, and ERAP2) presented causal associations with skin cancer." (PMID 41209561, 2025).
thyroid cancer (1 paper, 2022). "CPNE1 can act as potential biomarker to identify well-differentiated thyroid cancer tissue and normal thyroid tissues, which simplifies the process of early thyroid cancer diagnosis." (PMID 35139863, 2022).
cancer (15 papers, 2018 to 2025). A tumor composed of atypical neoplastic, often pleomorphic cells that invade other tissues. "Multiple studies have conclusively proven that CPNE1 was upregulated in malignancies and closely associated with the occurrence and development of cancer." (PMID 37077419, 2023). "Although the role of CPNE1 in cancer has been reported before, the underlying mechanisms are unclear." (PMID 29970127, 2018). "Therefore, while existing research predominantly focuses on the oncogenic role of CPNE1 in cancer, our and Ren’s study provide causal evidence through MR analysis, revealing the potential protective function of CPNE1." (PMID 39351539, 2024). "Although the causal role of CPNE1 has been reported in multiple cancer types, the function of CPNE1 in cellular senescence keeps unknown." (PMID 33274830, 2020). "Subsequently, we carried out a comprehensive expression-clinical analysis of CPNE1 in 33 types of TCGA cancer through LinkedOmics." (PMID 37077419, 2023). "Functional enrichment analysis revealed that CPNE1 and its co-expressed genes mainly regulated cancer-related and immune-related pathways." (PMID 37077419, 2023). "In terms of tumour stage and cancer grade, we found CPNE1 was highly expressed in grades 1‐4 and stages 1‐4." (PMID 35139863, 2022). "Since EMT is a critical progress that is involved in the initiation or maintenance of cancer metastasis in multiple malignancies, we further examined the regulatory role of CPNE1 in EMT process." (PMID 34977878, 2021). "The functional divergence presented by miR‐335 and CPNE1 in cancers implicates the complexity and heterogeneity rendered by various tumors." (PMID 34977878, 2021). "High expression of CPNE1 was correlated with poor prognosis and clinical progression in various cancers." (PMID 34743202, 2021). "Accumulating evidence reveals a key role of CPNE1 in cancer progression and metastasis." (PMID 37077419, 2023). "Our previous studies confirmed that CPNE1 plays an important role in the development of cancer." (PMID 34743202, 2021). "Phenotype scanning revealed that seven out of the thirteen identified proteins (KDELC2, GSTP1, CTSS, CPNE1, ISLR2, SFTPB, and ICAM5) were associated with other traits, but none of these traits were likely to bias the associations between identified proteins and cancers." (PMID 37735436, 2023). "Although we focused on RBM15 and serine metabolism in this study, network analysis revealed that the relationship between RBM15 and other genes with oncogenic potential (CDC42, CDC14B, STK40, BRD3, CPNE1, and MCM3) is also crucial for cancer cell survival." (PMID 38825643, 2024). "CPNE1 was highly expressed in HCC tissues and significantly correlated with sex, age, cancer stage and tumor grade." (PMID 35139863, 2022). "CPNE1 is overexpressed in HCC cell lines compared with most tumor types, which was obtained by the Cancer Cell Line Encyclopedia (CCLE)." (PMID 35139863, 2022). "Here, we reported a novel molecular function of miR‐335 and CPNE1 in regulating cancer metastasis, by which increment of miR‐335 induced cell migration and invasion through binding to the 3′UTR of CPNE1 for inhibiting its mRNA stability." (PMID 34977878, 2021). "Continued research in this area may reveal their therapeutic potential, particularly KDELC2, TNFRSF10B, CPNE1, and PDIA3, paving the way for more effective cancer treatments." (PMID 37735436, 2023). "Among 14 paired cancer tissues, negative or low protein expression of CPNE1 was detected in 4 samples, and high expression was detected in 10 samples, while 57% were negative for NEDD4L expression and the rest were positive." (PMID 34743202, 2021). "In the present study, although the evidence shows that dysregulated expression of CPNE1 is due to target binding of miR-335-5p in NSCLC, it is not surprising that other miRNAs may target CPNE1 and exert the same biological function in NSCLC or other human cancers." (PMID 29970127, 2018).
tumor (14 papers, 2018 to 2026). "Though recent studies revealed that overexpression of CPNE1 improved tumor proliferation and metastasis, associated with poor prognosis and malignancy." (PMID 34977878, 2021). "Further clustering of the tumor cells identified six cell subpopulations, among which multiple Copines genes, especially CPNE1 and CPNE3, showed a high expression." (PMID 40337972, 2026). "PAK4, CPNE1, and MCT4 are predicted to each have miR-330-5p binding sites and are tightly linked to tumor metabolism or glycolysis." (PMID 37532687, 2023). "TIMER was used to find out differences in mRNA expression of CPNE1, between tumor and normal tissue, in multiple cancers." (PMID 37077419, 2023). "Elevated CPNE1 expression was related to advanced tumor stage, histological grade, distant metastasis, and shorter survival time." (PMID 37077419, 2023). "The relationships between CPNE1 and tumor immunology were explored using ESTIMATE and CIBERSORT method." (PMID 37077419, 2023). "There was also a significant correlation between CPNE1 expression and tumor immune infiltration in HCC." (PMID 35139863, 2022). "Last, more experiments should be done to further investigate the effects of CPNE1 on tumor immune infiltration." (PMID 35139863, 2022). "Collectively, these results suggested that CPNE1 is a tumor suppressor in regulating EMT progression, preventing the migration and invasion of LAC cells." (PMID 34977878, 2021). "However, mutations in genes CPNE1, CTSB and ELN, indicated that their expression was slightly higher in tumor samples than in normal ones." (PMID 38544823, 2024). "Additionally, other research has demonstrated that CPNE1 is overexpressed in TNBC tissues and cell lines, closely associated with tumor size, distant metastasis, and the survival rates of TNBC patients." (PMID 39351539, 2024). "CPNE1 was significantly upregulated in 15 tumor types including KIRC." (PMID 37077419, 2023). "Lastly, the effect of CPNE1 on tumor immunity will be further investigated." (PMID 37077419, 2023). "Overall, these results indicated that CPNE1 might play an important role in regulating tumor immunity, and act as a potential therapeutic biomarker for ccRCC immunotherapy." (PMID 37077419, 2023). "CPNE1, a tumor-related gene, plays the role of proto-oncogene to promote tumor development." (PMID 35139863, 2022). "Moreover, after adjustments for tumor purity, the CPNE1 expression level was significantly correlated with 53 out of 61 immune cell markers in LIHC." (PMID 35139863, 2022). "Previous studies have shown CPNE1 is upregulated in multiple tumor types." (PMID 35139863, 2022). "There was a significant correlation between CPNE1 expression and tumor immune infiltration in LIHC." (PMID 35139863, 2022). "CPNE1 is observed to be upregulated in multiple tumor tissue compared to normal tissues." (PMID 35139863, 2022). "Also, the silencing of copine 1 (CPNE1), a TRAF2 interactor, induced cell cycle arrest in PCa cells and this anti-tumor effect was reversed by overexpressing TRAF2." (PMID 40229245, 2025). "Interestingly, genes with oncogenic potential, including CDC42, CDC14B, STK40, BRD3, CPNE1, and MCM3, were downregulated, whereas tumor inhibitors, including CDKN2C, CASP7, and CDKN1B, were upregulated by RBM15 depletion." (PMID 38825643, 2024). "Assessing the T cell infiltrate in KPCpne1 and KPmCherry tumors revealed that Cpne1-expressing tumor cells were not highly immunogenic as neither CD8+ T cell infiltration nor activation were significantly different between both tumors." (PMID 37548358, 2023). "Thus, we hypothesized that microRNA-mRNA interactions accounted for the differential expression of CPNE1 in ADC and SCC tumor subtypes." (PMID 32201531, 2020). "We evaluated the expression levels of CPNE1 and NEDD4L in lung tissues (tumor specimens and adjacent non-tumor specimens) by Western blotting." (PMID 34743202, 2021).
CPNE1 also shares sentences with these, for which no sentence is quoted: lymph node metastasis (3 papers); clear cell renal cell carcinoma (1); colon adenocarcinoma (1); head and neck cancer (1); Hepatitis (1); kidney cancer (1); melanoma (1); mesothelioma (1); Obesity (1); ovarian cancer (1); squamous cell carcinoma (1); stomach cancer (1).